B2M (beta-2-microglobulin)
Diseases named in the same sentence as B2M in open-access papers (continued):
Sharing a sentence is not in itself a finding about the gene and the disease.
melanoma (continued). "As expected, we found a correlation between presence of B2M+/MITFhigh melanoma cell populations and CD8+ (Spearman cor." (PMID 38594286, 2024). "We first examined the role of antigen presentation by challenging mice with β2-microglobulin–KO (B2m–/–) B16 melanoma cells, which are unable to present antigen to CD8+ T cells." (PMID 38861331, 2024). "Expression of TAP1, TAPBP, and B2M was higher in 5hmC-high melanoma samples than 5hmC-low samples, indicating a positive correlation between TET2 activity and MHC I antigen-presenting genes." (PMID 39388288, 2024). "More interestingly, somatic loss of heterozygosity (LOH) at the HLA-I gene locus and mutations in B2M or at least one HLA-I gene were both associated with higher NEO2IS in NSCLCs and melanomas." (PMID 37100920, 2023). "Methylation reactions in the TME of melanoma impact the expression of B2M and SPI1, which controls CD1D expression." (PMID 37077920, 2023). "Five PD1 PROG melanoma cell lines displayed homozygosity of HLA-A alleles concurrently with other resistance effectors, including loss of PTEN (4/5) and loss of B2M (1/5)." (PMID 36934113, 2023). "For example, in melanoma, mutations in JAK1/JAK2 (Janus Kinase 1/2) and B2M (beta-2-microglobulin) genes associated with acquired resistance to ICIs, and STK11/LKB1 mutations in KRAS mutated lung adenocarcinoma, have been documented." (PMID 38136385, 2023). "Next, melanoma patients were sorted accordingly to B2M differential expression (high to low B2M expression)." (PMID 37077920, 2023). "Expression of other members of the antigen presenting machinery including B2M were also increased in response to 5-NL treatment in melanoma cells." (PMID 37582744, 2023). "To assess this, we engineered a human B2M-KO melanoma line (M202-β2mKO) to express the mouse NKG2DL RAE-1d." (PMID 37537301, 2023). "We next characterized NK and T cells in mice on day 14 post-tail vein injection of WT and B2m-/- B16 melanoma cells." (PMID 36733396, 2022). "Taking into account the many recent advances in B2M-related melanoma immunity, here we discuss the immune function of the B2M gene in tumors, its common genetic alteration in melanoma, and its impact on and related improvements in melanoma immunotherapy." (PMID 36046045, 2022). "Combination therapy with bempegaldesleukin and ICI revealed a synergistic antitumor effect, and the systemic administration of bempegaldesleukin attenuated anti-PD-1 resistance in B2M knockout tumors and prolonged survival in B2M knockout melanoma mice." (PMID 36046045, 2022). "A variety of genetic defects in B2M were observed in tumor biopsies of 29.4% of patients with metastatic melanoma which is higher than primary melanoma." (PMID 36046045, 2022). "Based on the pivotal role of T cells in curbing melanoma metastatic foci growth in the lungs, we assessed the infiltration of CD4+ and CD8+ T cells in the lungs on day 14 following the tail vein injection of WT and B2m-/- B16 melanoma." (PMID 36733396, 2022). "We found that PD1+ IVpos CD4+ T cells remained comparable between the control and WT and B2m-/- B16 melanoma-challenged mice (“CD4”)." (PMID 36733396, 2022). "MHC-I, TAP1 and B2M expression were found to be up-regulated after treatment of melanoma cells with BO-112, an activator of dsRNA sensing and NF-κB signalling, restoring the cytotoxic activity of tumour-specific T cells." (PMID 35343573, 2022). "Quantifying IVneg NK cells in the lungs revealed a slight but significant enrichment of lung-infiltrating NK cells in WT B16 melanoma cell-injected mice, which further increased in mice injected with B2m-/- B16 melanoma cells." (PMID 36733396, 2022). "In contrast, among IVneg lung-infiltrating NK cells, we found significantly increased cNK cells and decreased CD49b-CD49a+ tissue-resident NK (trNK) cells proportions upon WT and B2m-/- B16 melanoma challenge." (PMID 36733396, 2022).
melanoma (continued). "In contrast to NK cells, IVpos and IVneg T cells showed robust expression of IFNγ in the lungs of WT and B2m-/- B16 melanoma-challenged mice compared to control animals." (PMID 36733396, 2022). "We assessed the impact of ACB1801 on the expression of antigen presentation genes (TAP1, TAP2, Tapasin, b2m, Lmp2, Lmp10, PA28α and PA26β) in murine B16-F10 melanoma." (PMID 36458012, 2022). "The majority of IVpos circulating NK cells in the lung were CD49b+CD49a- conventional NK (cNK) cells in WT, B2m-/- B16 melanoma-challenged and untreated mice." (PMID 36733396, 2022). "A similar alteration in B2M with corresponding LOH was also found in a melanoma patient who had a partial response to nivolumab." (PMID 36046045, 2022). "In contrast, PD1 expression on IVneg CD4+ T cells from the lungs was significantly elevated in WT and B2m-/- B16 melanoma-challenged mice (“CD4”)." (PMID 36733396, 2022). "The exploration of potential clinical implications of the B2M gene in melanoma immunity is just starting." (PMID 36046045, 2022). "After transfection of wild-type B2M gene, melanoma cells with B2M defects restored sensitivity to T cell lysis and ability to induce T cell IFN-γ secretion in an HLA-restricted manner." (PMID 36046045, 2022). "Intravenous WT and B2m-/- B16 melanoma challenge resulted in a significant increase in the proportions of granzyme B/perforin positive IVneg NK cells in the lungs." (PMID 36733396, 2022). "TNFα expression in IVpos circulating and IVneg lung-infiltrating NK cells was significantly enhanced in the lungs of mice that received WT and B2m-/- B16 melanoma cells." (PMID 36733396, 2022). "B16 melanoma cell line with endogenous expression of MHC-I (WT B16) and with loss of MHC-I through B2m gene deletion (B2m-/- B16) were utilized." (PMID 36733396, 2022). "Upon lung infiltration, IVneg CD4+ and CD8+ T cells significantly upregulated TNFα expression in WT and B2m-/- B16 melanoma-challenged mice compared to the controls." (PMID 36733396, 2022). "Based on this, B2M gene defect and T cell-based immunotherapy can interact to affect the efficacy of melanoma treatment." (PMID 36046045, 2022). "Our comprehensive review of β2M biology and its role in tumor immunotherapy contributes to understanding the potential of B2M gene as a promising melanoma therapeutic target." (PMID 36046045, 2022). "Next, we assessed lung-recruited NK and T cells on day 14 post-tail vein injection of WT and B2m-/- B16 melanoma cells." (PMID 36733396, 2022). "WT and B2m-/- B16 melanoma challenge significantly reduced the IVneg proportions of DN and CD11b-CD27+ precursors and increased functionally dynamic and mature NK cell populations comprising DP and CD11b+CD27- NK cells." (PMID 36733396, 2022). "At the end of 3-week mavorixafor monotherapy, expression scores for a panel of antigen processing and presentation genes measured in melanoma biopsies, which included B2M, TAP1/TAP2, and multiple HLA complex genes, trended toward an increase." (PMID 36923305, 2022). "Of note, among IVneg immune effector populations in the lungs, T cells, especially CD4+ T cells, showed the most robust increase in response to WT and B2m-/- B16 melanoma challenge compared to the untreated control mice." (PMID 36733396, 2022). "Our data illustrate the importance of this mechanism outside melanoma and the need to evaluate B2M LOH as exclusion criterion for ICB or prioritization for NK cell therapy." (PMID 34446728, 2021). "In contrast to other tumor types including melanoma or non-small cell lung cancer, MSI colorectal cancers display biallelic B2M mutations in up to 30% already at the time point of diagnosis." (PMID 34168989, 2021). "More recently, Zaretsky and colleagues showed that truncating alterations in B2M were one of the recurring findings in acquired resistance of melanoma to anti PD-1." (PMID 34072037, 2021).
melanoma (continued). "This association between B2M LOH events and ICB resistance has been demonstrated in three independent melanoma cohorts." (PMID 34446728, 2021). "Among those we found JunB, B2M, and Narf2—markers of inflammation, cell exhaustion, and melanoma oncogenic programs taking place in malignant and T cells." (PMID 34872616, 2021). "Focal somatic pathogenic alterations occurred in B2M and GRIN2A genes encoding transmembrane proteins, the latter gene being mutated in metastatic glioblastoma and frequently, in melanoma." (PMID 32680567, 2020). "As expected, the CYT score was positively correlated with the expression of the MHC class I genes in the 79 melanoma biopsies with RNA sequence data (Pearson correlations of 0.61, 0.77, 0.74 and 0.74 for HLA-A, -B, -C and B2M)." (PMID 32312968, 2020). "Inactivating mutations in the antigen presentation pathway such as mutations in beta 2 microglobulin (β2M) and JAK1/2 can influence the ability of melanoma cells to present peptides to the immune system." (PMID 33276788, 2020). "It was shown that DUX4 expression in various cancer cells correlates with reduced expression of HLA class I genes including B2M and promotes resistance to immune checkpoints inhibitors in melanoma patients." (PMID 32517213, 2020). "It was shown that the proper expression of B2M positively correlates with the overall survival of melanoma patients during immunotherapy." (PMID 32517213, 2020). "Mechanisms of acquired resistance to checkpoint inhibitors include loss of IFNγ-transducing signaling pathways JAK1 and JAK2, loss of antigen presentation (B2M) and activation of the PTEN/PI3K pathway in pembrolizumab-treated melanoma patients." (PMID 31647026, 2019). "The combination of B2M gene mutation and HLA class I heavy chain or APM downregulation within a single tumor cell population has been described in melanoma." (PMID 30648121, 2018). "For instance, the genetic loss of the β-2-microglobulin (B2M) gene, the structural component of MHC class I complexes, is enriched in pre-treatment tumor samples from melanoma patients with innate and acquired resistance to checkpoint inhibitor therapy." (PMID 29977240, 2018). "Here, the authors demonstrate that B2M loss is a mechanism of primary and acquired resistance to therapies targeting CTLA4 or PD-1 in melanoma patients." (PMID 29070816, 2017). "Using the CRISPR/Cas9 technology, we introduced a guide RNA and deleted B2M in a melanoma cell line derived from BRAFV600E; PTEN−/− transgenic mice." (PMID 29070816, 2017). "In this model, B2M is only inactivated in melanocytes and melanoma cells." (PMID 41109214, 2025). "Recently, acquired resistance to pembrolizumab was reported in a patient with advanced melanoma, which might be attributed to B2M defect." (PMID 40191187, 2025). "Additionally, ICI-resistant melanomas can have point mutations, deletions or loss of heterozygosity (LOH) in B2M, thus causing disturbances in the presentation of MHC-I, preventing the identification of melanoma cells by the immune system." (PMID 40108693, 2025). "Irreversible alterations such as B2M mutations and HLA class I loss of heterozygosity (LOH) are frequently observed in melanoma, lung cancer, and microsatellite instability–high colorectal cancer, particularly in tumours that relapse after immune checkpoint blockade." (PMID 40673641, 2025). "Currently, B2M mutation comprises point mutation, frameshift mutation, and loss of heterozygosity (LOH), which have been documented in malignant tumors like gastric cancer, colorectal cancer, renal cancer, and melanoma." (PMID 40191187, 2025). "Moreover, the interferon target gene, β–2-microglobulin (b2m) is one of the top down-regulated genes in TIE:EGFP expressing melanoma cells." (PMID 38874379, 2024). "B2M loss or mutation, and consequently deficient MHC-I antigen presentation, is a well-described mechanism of tumor-intrinsic resistance for immunotherapy-treated patients in several melanoma studies." (PMID 37057033, 2023).
melanoma (continued). "To address the translational relevance, we performed in vitro cytotoxicity experiments using the M202 human melanoma line (human leukocyte antigen (HLA)-A*0201), which expresses the MART-1 tumor-associated antigen, or an MHC-I-negative B2M-KO version of the same cells (M202-β2mKO)." (PMID 37537301, 2023). "Losses and mutations in these genes have been linked to primary and acquired resistance to PD-1 blockade in melanoma, suggesting that melanoma cells become insensitive to the antiproliferative effects of IFNγ (via JAK1/2 alterations) or lose antigen presentation (via B2M alterations)." (PMID 36977461, 2023). "In addition to circulating NK cells, liver NK cells in mice that received WT and B2m-/- B16 melanoma were activated compared to the control mice on day 14-post melanoma challenge." (PMID 36733396, 2022). "Many in vitro experiments have shown that using the plasmids or adenoviruses strategy to deliver wild-type human B2M gene into melanoma cells or other tumor cells can restore tumor cell HLA class I antigen expression and peptide-specific T lymphocyte recognition." (PMID 36046045, 2022). "The results indicated that HLA-DRB5 had significantly higher mutation frequency in responders and the B2M mutations only occurred in non-responders in melanoma." (PMID 36139377, 2022). "B2M loss is the initial genetic alteration in the development of MHC class I loss, as the structural alteration in the B2M gene can be detected even in HLA-positive melanoma cells." (PMID 36046045, 2022). "New technologies and hypotheses in melanoma tumor immunity are increasingly explored, which may provide additional insights into our understanding of the role of B2M in tumor immunity." (PMID 36046045, 2022). "Mutations, loss of heterozygosity, and deletions in B2M were previously identified in non-responding melanoma patients to immunotherapy." (PMID 34725325, 2021). "Similarly, melanoma patients, receiving anti–PD-1 therapy (pembrolizumab), developed immune escape lesions with LOH in JAK2 and a truncating mutation in B2M." (PMID 34680201, 2021). "The B2M-positive tissues of patients before the ICI treatment and an absence of B2M in lesions of patients with melanoma progression implies that the loss of B2M is responsible for acquired resistance." (PMID 34356899, 2021). "Although acquired mutations in Janus Kinase (JAK) 1, JAK2, and beta 2-microglobulin (B2M) are markers of resistance to PD-1 blockade in melanoma, their role in patients with CRC is not yet well defined." (PMID 32090113, 2020). "Diminished expression of HLA-ABC (~80% reduction in expression) was driven by two independent B2M-targeting silencing molecules and this significantly reduced the immune recognition of melanoma cells, leading to approximately a 70% reduction in the levels of IFNγ production." (PMID 32312968, 2020). "Further, a more direct evidence revealed that loss of heterozygosity (LOH) at B2M locus happened three folds higher in non-responders compared with responders from a cohort of melanoma patients treated with PD1 blockade." (PMID 32793604, 2020). "For instance, in melanoma, B2M gene alterations have been linked to ICI resistance, although in microsatellite instability-high colorectal carcinomas, patients with mutant B2M still benefited from immunotherapy." (PMID 33260693, 2020). "One may suggest that the PCR data identified HLA antigens on infiltrating cells, however all original studies were performed using immunohistochemistry on tumor sections, analyzing melanoma-cell specific HLA class I and II and B2M expression." (PMID 27764126, 2016). "Melanomas tend to have an extremely high mutational burden in comparison with other tumor types, which could logically reduce the chance that JAK or B2M mutations might arise." (PMID 27782862, 2016).
melanoma (continued). "A clinical study reported that among 181 melanoma patients, 78 cases (43%) exhibited either complete or predominant (> 50%) loss of MHC‐I expression, which was linked to reduced transcription of HLA‐A, HLA‐B, HLA‐C and B2M, and closely linked to primary resistance to anti‐CTLA‐4 therapy." (PMID 40673641, 2025). "Acquired resistance to anti-PD-1 ICI in patients with melanoma has been reported to be associated with defects in the pathways involving interferon-receptor–associated Janus kinase 1 (JAK1) or Janus kinase 2 (JAK2), as well as in the antigen-presenting protein beta-2-microglobulin (B2M)." (PMID 40236650, 2025). "Genetic alterations such as B2M mutations or deletions in antigen‐processing machinery (e.g., TAP1/2, ERAP1/2) are associated with clonal and irreversible MHC‐I loss, frequently observed in melanoma, colorectal, and lung cancers, and have been linked to primary resistance to PD‐1/PD‐L1 blockade." (PMID 40673641, 2025). "Notably, one of the PD1res MITFhigh melanomas harbored a B2M genetic alteration." (PMID 38594286, 2024). "As expected from the in vitro experiments, TILs were not able to eradicate B2M deficient melanoma in the PDXv2 model, but CAR-TILs could." (PMID 36765608, 2023). "Therefore, we sought to evaluate whether B2M and CD1D gene expression is governed by epigenetic changes associated with DNA methylation in the tumor microenvironment of melanoma." (PMID 37077920, 2023). "Defects in the B2M gene may be an effective predictive marker for ICB therapy in melanoma." (PMID 36046045, 2022). "After an early analysis of molecules involved in functional HLA class I Ag expression in melanoma cell lines originating from recurrent metastases after initial T cell-based immunotherapy, three types of B2M gene mutations resulting in a lack of translation of the β2M were identified." (PMID 36046045, 2022). "Besides misdiagnosis of MMR-proficient tumors as MSI, non-functionality of tumor cells’ antigen presentation machinery, mediated by mutations of the Beta2-microglobulin (B2M) gene, has been discussed as a key mechanism of resistance towards ICB in some cancer types, such as melanoma." (PMID 34168989, 2021). "While loss of beta-2 microglobulin, a membrane protein component of the MHC class I has been associated with acquired resistance to anti-PD1 blockade in melanoma, upregulation of other genes in the antigen processing pathway may alter the neoantigen landscapes that results in immune evasion." (PMID 33177175, 2020). "Sucker at al. described clinical cases of melanoma patients treated and not treated with immunotherapy, whose progressed lesions evolved into complete loss of the B2M gene, which was accompanied by decreased infiltration of T cells due to the loss of HLA class I and II proteins." (PMID 32517213, 2020). "Neither mutation nor gene expression change in JAK1, JAK2, B2M, HLA-A, HLA-B, and HLA-C was observed between pre- and post-treatment tumor samples, which were previously indicated to be associated with resistance to PD-1 antibody treatment in melanoma." (PMID 30872362, 2019). "It is tempting to hypothesize the association between B2M duplication and melanoma regression in pigs; however, we do not have any direct evidence to support this hypothesis." (PMID 28813459, 2017). "Here, we tested the efficacy of mIL12 mRNA as a single agent and in combination with anti-PD-L1 antibodies in ICI sensitive Yummer1.7 melanoma and MC38 colorectal murine tumors and in ICI resistant, β2-microglobulin (B2M) knockout versions of these models." (PMID 40321762, 2025). "Furthermore, it has been demonstrated that loss of heterozygosity (LOH) at the B2M locus occurred three times more frequently in non-responders than in responders, and loss of both copies of B2M was found only in non-responders among patients with melanoma treated with anti-PD-1." (PMID 40001572, 2025).